IL6 (interleukin 6)
Diseases named in the same sentence as IL6 in open-access papers (continued):
Sharing a sentence is not in itself a finding about the gene and the disease.
tumor (continued). "Beside interleukin-6 (IL-6), the high level of which is observed in patients with a high mortality rate, other cytokines IL-17A, IL-22, and transforming growth factor -β (TGF-β) are expressed at the tumor level." (PMID 36361758, 2022). "Clinical results have shown that myCAFs have a synergistic effect on T cells and inhibit tumor growth, while inflammatory CAFs promote tumor growth and immunosuppressive response by secreting ECM proteins and cytokines such as IL-6, IL-11 and leukemia suppressors." (PMID 35965504, 2022). "In both the tumor and spleen of the ApcMin/+ mice, IHS strongly suppressed the expression of IL-5 (p < 0.05), IL-6 (p < 0.05), IL-10 (p < 0.05), P-JAK1 (p < 0.05), P-JAK2 (p < 0.05), P-STAT3 (p < 0.05), and P-STAT5 (p < 0.05) and enhanced the P-STAT1 expression (p < 0.01)." (PMID 36014805, 2022). "Irradiated tumor cells undergo immunogenic cell death, which leads to the release of DAMPs and an increase in the concentration of cytokines, such as IFN-γ, IL-1, TGF-β, and IL-6, followed by the stimulation of DCs." (PMID 36010838, 2022). "In TME, IL-6 could drive tumor cells proliferation, invasiveness, and metastasis through activating JAK/STAT3 signaling pathway which could in return promote IL-6 transcription." (PMID 36685973, 2022). "Additionally, tumor-derived MYDGF promotes the release of inflammatory cytokines including TNF-α and IL-6 and increases macrophage infiltration, all of which ultimately aid in the growth of tumors." (PMID 36071472, 2022). "As an example, to evade the attack of effector immune cells, tumor cells can produce immune suppressive factors, such as IL-6, IL-8, and transforming growth factor-β (TGF-β) to recruit immunosuppressive cells and impair the anti-tumor immune response, favoring tumor progression." (PMID 36145516, 2022). "Besides IL-6, scientific evidence has also pointed towards IL-8, the ligand of CXCR2, to be a critical player in the maintenance of inflammation, tumor growth and also angiogenesis." (PMID 35965494, 2022). "However, inhibition of miR-21 significantly reduces the polarization of M2 GAMs and decreases levels of VEGF, TGF-β1, and IL-6 by decreasing activities of Sox2, PDCD4, and STAT3, ultimately inhibiting GBM tumor cell growth." (PMID 35572545, 2022). "Among the top enriched signaling pathway network, the interactions between THBS2+ CAFs and other cells within the tumor micro-ecosystem were most mediated by THBS, followed by stromal/immune signaling pathways, e.g. THY-1, FN-1, TGF-β, IL6/4, MHC-I, VEGF, CD40, or TIGIT." (PMID 35547750, 2022). "In the present study, the levels of IL-6 and SAA increased with tumor stage." (PMID 36316846, 2022). "Other indirect mechanisms were also reported to be involved in tumor cells elimination by M1-type macrophages such as the expression of cytokines (IFN-γ, IL-1, and IL-6) that activate the cytotoxic Th1 cells leading to an antitumoral immune response activation." (PMID 35493456, 2022). "Furthermore, based on the stratified analysis at tumor stage (stages I/II/III), we observed that LAGC patients with high levels of IL6_0 and TNFα_0 at advanced tumor stage have poor prognosis by the description of Kaplan-Meier curves." (PMID 35859928, 2022). "It was established that IL-6 promotes the activation of STAT3, and accordingly, tumor development." (PMID 35567250, 2022). "Moreover, IL-6 is the main pro-inflammatory factor responsible for inducing the overexpression of tumor-related RAC1B, known to sustain tumor cell survival and promote escape from oncogene-induced senescence." (PMID 35681689, 2022).
tumor (continued). "Extensive research has shown that intestinal microbes stimulate the expression of chemokines such as TNF- α, IL-6, IL-10, and IL-1β or activate cytotoxic lymphocytes, such as CD4+ and CD8+ T cells or NK and NKT cells, in both peripheral blood and tumor to limit tumor growth." (PMID 36232344, 2022). "Moreover, IL-1β activates the NF-kB signaling pathway of myeloid-derived suppressor cells (MDSCs), which increases IL-6 and TNF-α secretion, enhancing tumor growth." (PMID 35892729, 2022). "The location of HMGB1 in the cytoplasm or extracellular space will promote the release of cytokines such as IL-6 and IL-8 by activating MAPK- and MyD88-dependent NF-KB pathways, thereby prompting tumor cell proliferation, angiogenesis, EMT, invasion, and metastasis." (PMID 35273678, 2022). "The expression of inflammatory cytokines, such as TNF-α, interferon-gamma (IFN-γ), IL-1, and IL-6, which act as anti-tumor effectors, did not vary between the sensitive and resistant groups." (PMID 35965549, 2022). "Our data support previous work showing that tumor IL-6 impacts myelopoiesis and MDSC, but importantly it also positions tumor-derived IL-6 as a negative regulator of the total CD4+ Th cell population, an effect that is particularly pronounced locally in the tumor." (PMID 36142210, 2022). "The binding of IL-6 to its receptor elicits the downstream activation of multiple signaling pathways including the JAK-STAT3 pathway, which promotes cell cycle progression, tumor invasiveness, and host immune-system evasion." (PMID 35406450, 2022). "Previous study demonstrated that DLBCL has pro-tumor mechanisms by expressing IL-6/IL-6R and inhibiting negative regulator, eventually promoting the constitutive activation of IL-6/IL-6R axis." (PMID 36104733, 2022). "For this reason, the most critical proinflammatory cytokines involved in tumor progression, such as IL-6 and IL-1, cannot represent therapeutic targets without compromising the patients’ antitumor immunocompetence." (PMID 36362718, 2022). "Notably, it was discovered that TGF-β receptor 2 blockade reduced IL-6 from CAFs, resulting in a reduction of STAT3 activation in cancer cells and improve the anti-tumour immune response." (PMID 36284087, 2022). "IL-6 also activates the Janus kinase (JAK) signal transducer and activator of the STAT3 (signal transducer and activator of transcription 3) pathway, leading to adverse effects in tumours, such as reduced apoptosis in HCC cells." (PMID 35572649, 2022). "It was shown that neutralization of human IL-6 by monoclonal antibodies reduced tumor-induced cachexia independent of an effect on tumor growth in human tumor xenograft models in nude mice, supporting a role for tumor-derived IL-6 in cancer cachexia." (PMID 36471329, 2022). "Enhanced IL-6 serum levels in STS (including LPS) patients correlated with higher tumor grade and were a negative prognostic factor for OS, DFS, and event-free survival." (PMID 36230502, 2022). "Moreover, the inflammatory IL-6/STAT3 regulatory circuit, which is maintained by pancreatic stromal cells in the TME, modulates tumor aggressiveness and metastatic properties." (PMID 35993361, 2022). "CAFs, in contrast, express paracrine molecules that promote tumour growth and therapy resistance, including growth factors (CTGF, EGF, and PDGF), chemokines (CXCL1, CXCL5, CXCL7, CXCL8, CXCL12, and CCL12), and cytokines (IL-6, IL-11, and LIF)." (PMID 36284087, 2022). "Experience with biologic DMARDs is limited, but some cases reported satisfactory responses with IL-6 inhibitors or TNF-α inhibitors without a significant impact on tumor response." (PMID 35783644, 2022). "IL‐6 and VEGF were undetectable in the plasma of both HCT116 and A549 tumour‐bearing mice." (PMID 35701366, 2022). "Likewise, most ICD-related genes, including IL-6, IL-10, NLRP3, CD8A, CD8B, and TLR4, exhibited attenuated expression levels in tumor cells compared to normal cells." (PMID 36225939, 2022).
tumor (continued). "Interestingly, M1-like anti-tumor macrophage-derived EVs can transport higher mRNA amounts of M1 markers, including CD86, IL-6, TNF-α and iNOS, toward M2 macrophages and further induce M2 to M1 repolarization." (PMID 35927755, 2022). "We also performed IHC multiplex staining for IL6, PAX8 (HGSOC tumor marker), and CD3 on HGSOC patient biopsies and observed IL6 brown staining colocalized in areas with purple tumor cells and some blue tumor-infiltrating lymphocytes." (PMID 35313341, 2022). "SERPINE1 could induce angiogenesis and tumor inflammatory microenvironment, in which anoikis was a critical player, by regulating the expression level of VEGF and IL-6 via VEGF and JAK-STAT3 inflammatory pathways." (PMID 36685842, 2022). "IL-6 induces tumor pro-survival and pro-proliferation signaling by activating signal transducers and activators of transcription (STAT) 3, and promotes tumor immune escape by further inhibiting the activation of DCs, NKs, and T cells." (PMID 36092724, 2022). "Here, the IL‐6/JAK/STAT3 pathway was downregulated on Day 7 (NES = −1.65, FDR = 0.003) and Day 14 (NES = −1.63, FDR = 0.003), suggesting that modulation of this pathway is partially responsible for the observed NTP effects on tumor kinetics and mouse survival." (PMID 36176603, 2022). "Tumor xenografts composed of P. gingivalis-infected OSCC cells exhibited higher resistance to Taxol through Notch intracellular domain 1 activation, and a higher serum level of IL-6 was detected compared with uninfected mice." (PMID 35847109, 2022). "In addition to preventing primary T-cell activation, MDSCs secret IL-6 to attenuate functional differentiation of the tumor-specific cluster of differentiation 4+ (CD4+) T cells into effector Th1 cells and promote tumor progression." (PMID 35954156, 2022). "To explore a mechanistic link between tumor-infiltrating neutrophils and iCAF-mediated IL-6/STAT-3 signaling in the PDAC TME, we characterized the secretome of tumor-infiltrating Ly6G+F4/80- neutrophils isolated from orthotopic KPC tumors, revealing IL-1β as the most robustly secreted cytokine." (PMID 36107485, 2022). "Finally, suppression of IL6 and IL8, genes shown to be repressed by ERβ in the present study, have also been shown to potently inhibit proliferation, migration, and tumor formation of TNBC cells." (PMID 35177654, 2022). "Highly expressed p-STAT3 was positively correlated to high levels of IL-4, IL-6, and IL-10, and negatively correlated to low levels of IFN-γ in the serum, which may contribute to immune surveillance disability against tumor cells." (PMID 35530361, 2022). "It has been reported that the absence of ADAM17 is sufficient to inhibit IL-6 trans-signaling-mediated tumor formation in the ApcMin/+ model." (PMID 36270986, 2022). "In addition, studies in breast cancer patient-derived xenografts (PDX) have also shown that IL-6 and IL-8 release by CD10+ GPR77+ CAFs increases cancer stem cell activity via persistent activation of NF-κB to support tumor survival and chemotherapy resistance." (PMID 36671452, 2022). "In addition, GSEA concluded that MS4As were involved in several tumor-related pathways, including TNF-α via NF-kB signaling, IL6/JAK/STAT3 signaling, IFN- γ response, IFN-α response, and epithelial–mesenchymal transition (EMT)." (PMID 35734424, 2022). "In addition, TGF-β, JAK/STAT, and IL-6/STAT3 signaling pathways contributed prominently to the stemness regulation of CD44+ cells, resulting in their vital roles in tumor initiation and growth." (PMID 36293184, 2022). "IL-6 overexpression is constantly detected in PCa patients and abnormal expression of IL-6 can activate the JAK-STAT signaling pathway and affect tumor growth by autocrine or paracrine loops." (PMID 35846361, 2022).
tumor (continued). "Gastric tumor-derived TEX was internalized by macrophages and induced an M1 pro-inflammatory response in macrophages through the activation of NF-κB, which stimulated inflammatory cytokines including GCSF, IL-6, IL-8, IL-1β, CCL2, and TNF-α and promoted tumor cell proliferation and migration." (PMID 35163380, 2022). "As one of the dominant cell types in the inflamed intestine, macrophages produce various cytokines, including IL‐6, IL‐12, IL‐23, IL‐1β and TNF, which modulate IEC activity and immune responses and evolve with and provide support to tumour cells during the transition to malignancy." (PMID 35363937, 2022). "Among the molecules that constitute the CSC secretome, we can find several interleukins (IL-6, IL-8, IL-1β), multiple MMPs and VEGF, all of which may be secreted either in a soluble form or inside tumor-derived vesicles." (PMID 36497411, 2022). "autophagy activated by RAGE promoted IL-6-induced STAT3 activation; in addition, downregulation of autophagic activity in RAGE-targeted knockout KC mice inhibited STAT3 activation and ATP generation in mitochondria and delayed tumor development." (PMID 35559037, 2022). "Instead, they activate immune cells, which leads to increased sympathetic activity, catecholamine synthesis, and browning in C26 (with high IL-6/PTHrP plasma levels) but not in C26nc (with low IL-6/PTHrP plasma levels) tumor-bearing mice." (PMID 35210363, 2022). "Significant co-expression of IL-6, Notch-1, and CD44 was also detected in the tumor tissues." (PMID 35953863, 2022). "Il-6 and Il-9 expression positively correlated in AOM/DSS tumour tissue." (PMID 35793807, 2022). "H&E staining results revealed that there were increased tumour nodules in both the control and single drug groups; however, tumour cell density was markedly reduced in response to the combination of NVP-BEZ235 and anti-IL-6 Ab." (PMID 35165269, 2022). "Furthermore, BC-MSCs recruit CXCR2+ neutrophils into TME, inducing a significant increase in expression of metastasis-related genes (CXCR4, CXCR7, MMP12, MMP13, IL-6 and TGF-β) in tumor cells and consequent metastasis." (PMID 35842634, 2022). "However, one emerging target is IL-6, which activates signal transducer and activator of transcription 3 (STAT3) signalling within tumour cells." (PMID 35020853, 2022). "Remarkably, prominent inflammatory and cancer-related pathways, such as interleukin-6 (IL-6) signalling, integrin signalling and nuclear factor-κB signalling, were significantly upregulated in the TF of metastatic vs non-metastatic tumours." (PMID 35022523, 2022). "Plasmodium infection could inhibit tumor secretion of Granulocyte-Macrophage Colony-Stimulating Factor human (GMCSF), IL-10, IL-6, C-C class chemokines (CCL)-17, and CCL-22 through the release of exosome-like vesicles." (PMID 36004920, 2022). "As subcutaneous IL-6 is known to decrease with fasting, combining IF with anti-VEGF therapy could have a beneficial impact on tumor growth." (PMID 35186923, 2022). "IL-6 was shown to be expressed by non-malignant α-SMA+ stromal cells within the primary tumor, likely acting on hepatocytes through the IL-6/JAK1/STAT3 axis." (PMID 35740692, 2022). "In turn, M2-like macrophages promote tumor deterioration by secreting growth factors, proangiogenic molecules (EGF, VEGFA), immunosuppressive factors (IL-6, IL-10, TGF-β, iNOS), and proteases that remodel the extracellular microenvironment such as matrix metallopeptidases." (PMID 35242705, 2022). "We review some beneficial bacteria that act on DCs, NK cells, cytotoxic T cells, and helper T cells to promote the secretion of the pro-tumor cytokines IFN-1, IFN-γ, and IL-2 and down-regulate the secretion of TNF-α, IL-6, IL-10, and IL-22, thus exerting anti-tumor immune effects." (PMID 36438840, 2022).
tumor (continued). "Similar to the process described for other tumor types, a vicious cycle exists when myeloma cells home to the marrow and release cytokines and factors that induce osteoclast activity and bone destruction, including TNF-α, IL-1, IL-3, and IL-6." (PMID 35646939, 2022). "Moreover, studies have suggested that several CAF-derived cytokines, including IL6 and LIF, can induce an EMT phenotype in tumor cells and an immune evasion in the tumor microenvironment to promote tumor progression in murine PDAC models." (PMID 35805064, 2022). "Furthermore, diacerin inhibits IL-6-induced STAT3 nuclear localization and transcriptional activity in TNBC cells, and significantly reduces tumor volume and induces apoptosis when compared to vehicle treated mice." (PMID 35371975, 2022). "In the intraperitoneal metastatic microenvironment, CAFs govern the metastatic cascade, including the adhesion, proliferation, invasion, and colonization of metastatic sites via increasing production of several molecules (CXCL12, IL-6, VEGFA, TGF-α, and β, FGF-1) within the tumor microenvironment." (PMID 35216340, 2022). "Previous reports postulated that IL-6, MCP-1, RANTES, and MMPs might involve in activating osteoclastogenesis, which in turn will support the tumor progression." (PMID 35243014, 2022). "For example, IL-6 interacts with the receptor JAK and induces STAT-3 activation, which triggers oncogenes such as myeloid cell leukemia-1 (MCL-1) and upregulates proliferative genes, Cyclin-D1, in tumor cells." (PMID 36613591, 2022). "Second, TRMBE and 5-FU combined therapy regulated the blood cytokines (IL-6, IL-10, TGF-β, IFN-γ), immune cells in spleen (PMN-MDSCs), and modulated the tumor microenvironment, most notably the percentage of infiltrating PMN-MDSCs, NK cells, and PD-1+ CD8+ T cells." (PMID 35656301, 2022). "The tumor antigens (including polypeptide, RNA, DNA, and tumor lysates) are loaded into the immature DCs, which are then presented on MHCs, and the various cytokines (for example, of GM-CSF, of IL-.4, of TNF-α, and IL-6 under) action to maturity." (PMID 35045874, 2022). "Besides, berberine inhibits tumor antigen-mediated IL-6 and TGF-β expression as well as IL-10 proliferation but restores anti-tumor cytotoxicity of T cells in the tumor microenvironment." (PMID 36439106, 2022). "M2 GAMs further produce more Arg-1, TGF-β, IL-10, IL-6, and other abundant immunosuppressive cytokines, thus foster immunosuppression and pro-angiogenesis which contribute to growth and invasion of GBM after GBM tumor cells adapt to the pro-inflammatory TME." (PMID 35572545, 2022). "Prior work from our group and others have revealed that inflammatory CAF (iCAF)-derived IL-6 engages in tumor-permissive crosstalk by activating STAT3 signaling with tumor cells, and that the CAF-tumor cell IL-6/STAT-3 signaling axis is a central mediator of chemoresistance in PDAC." (PMID 36107485, 2022). "In a murine model of colon cancer, lack of IL‐6 slows tumour growth and increase the infiltration of CD8+ T cells." (PMID 36124714, 2022). "The administration of calcipotriol to an autochthonous PDAC mouse model (KPC model) resulted in the decreased expression of several iCAF and myCAF markers, such as IL-6 and α-SMA, accompanied by the increased tumor vascular area and chemosensitivity of the developed tumors." (PMID 35884375, 2022). "Combination with IL‐6 blockade is not effective for sensitizing such tumor to ICI (anti‐PD‐1/anti‐CTLA‐4), but neutralization of IL‐6 along with stimulation of CD40 can cause tumor sensitization to ICI." (PMID 35301813, 2022). "Besides, the expression of IL-6 and TNF-α were upregulated while the expression of IL-10, CCL22, Arg-1 and CD206 were downregulated in the tumor tissues from ACEA-treated group." (PMID 35641479, 2022).